INS (insulin)
Diseases named in the same sentence as INS in open-access papers (continued):
Sharing a sentence is not in itself a finding about the gene and the disease.
diabetes (continued). "PI/IR is negatively correlated with insulin secretion in both healthy subjects and those with diabetes, implying that PI/IR may be a strong predictor of β-cell dysfunction." (PMID 24204660, 2013). "Furthermore, insulin resistance has been indicated as the physiological basis for MS, since it precedes diabetes, anticipating insulin secretion failure." (PMID 23363783, 2013). "In diabetes, the occurrence of insulin resistance is due to an alteration in insulin signaling." (PMID 24282409, 2013). "In support of our speculations about sex specific etiology of diabetes, a study of 1221 European men and women showed that male offspring of type 2 diabetes patients more often than female offspring had impaired insulin sensitivity and beta cell function." (PMID 23630613, 2013). "Whether this association reflects a contribution of endothelial dysfunction to accelerated decline of insulin sensitivity, or represents only an epiphenomenon accompanying pre-diabetes, remains to be elucidated." (PMID 23578341, 2013). "The release of these cytokines by adipocytes suggest that fructose-mediated diabetes may be related to systemic effects which include altered adiposity and insulin resistance." (PMID 23762544, 2013). "Moreover, ZnT8 plays a critical role in the synthesis and secretion of insulin and therefore represents a pharmacological target for treating disorders of insulin secretion including diabetes." (PMID 24265765, 2013). "Collectively, this study demonstrates that the long-term use of CSII therapy (insulinization) mimics physiological insulin secretion more effectively than other treatment strategies and provides a promising strategy for the treatment of diabetes mellitus type 2." (PMID 24223662, 2013). "Prevention of hypoglycemia while providing adequate insulin coverage is the challenge of diabetes management while traveling, and the use of a split basal insulin dose when traveling west or a reduced basal insulin dose when traveling east offers a safe, simple solution." (PMID 24360506, 2013). "NSNHEs also appear to have implications for diabetes management and the role that NSNHEs play in the disruption of optimal glycaemic control should be a considerable clinical concern given that 15.8% of respondents decreased their insulin dose after the NSNHE." (PMID 23350726, 2013). "It has been demonstrated previously that insulin could lower Lp(a) levels and an inverse relationship between the incidence of diabetes and Lp(a) has been reported." (PMID 24083682, 2013). "PMI5011 is a well-characterized botanical extract from A. dracunculus L., whose effects on carbohydrate metabolism are comparable to the ability of known antidiabetic drugs (troglitazone and metformin) to lower glucose and insulin levels in murine models of diabetes and insulin resistance." (PMID 23437325, 2013). "It is therefore relevant to explore how treatment with insulin and insulin analogs influence the behaviour of existing cancers, and to do this in animal models of diabetes or obesity combined with insulin resistance, since these factors are known risk factors for cancer development." (PMID 24260289, 2013). "MSCs can be differentiated into insulin-producing cells (IPCs) and could be an exciting therapy for diabetes but problems like poor engraftment and survivability need to be confronted." (PMID 23648189, 2013). "Vitamin K has been related to glucose metabolism, insulin sensitivity and diabetes." (PMID 23298335, 2013). "In view of these, peer support group may be effective to promote insulin acceptance among insulin naive diabetics as peer testimonies could facilitate insulin initiation and intensification." (PMID 24164794, 2013). "Insulin signals hepatocytes to increase glucose transport convert the glucose to glycogen; hepatic glycogen levels are reduced in patients with insulin resistance and diabetes." (PMID 23840313, 2013).
diabetes (continued). "XA might contribute to the development of diabetes via formation of chelate complexes with insulin (XA-In) and induction of pathological apoptosis of pancreatic beta cells through caspase-3-dependent mechanism." (PMID 24083022, 2013). "Previous research in the UK has documented that the automobile accident risk is lower among older drivers with insulin-treated diabetes compared with non-diabetic aged-matched controls." (PMID 23121373, 2013). "Cell size is reduced in STZ induced diabetes due to removal of the hypertrophic effect of insulin." (PMID 23327647, 2013). "Insulin therapy is usually required in those with HNF1B diabetes due to pancreatic atrophy." (PMID 24705260, 2013). "This ‘basal-plus’ strategy could increase the therapeutic options available to the person with diabetes, permitting further individualization of their insulin therapy, which may translate into increased clinical and functional benefits." (PMID 22998363, 2013). "Similar studies in individuals with pre-diabetes leads to decreased insulin secretory function." (PMID 23323566, 2013). "it is painful” (3 years of insulin use/ 6 years of having diabetes)." (PMID 24164794, 2013). "With the rising incidence of Type 2 diabetes in younger patients, the discovery of monogenic diabetes and development of new therapies aimed at preserving insulin secretion, the direct measurement of insulin secretion may be increasingly important." (PMID 23413806, 2013). "These misconceptions could reflect the participants’ poor knowledge regarding diabetes and insulin when they were first recommended for insulin." (PMID 24164794, 2013). "Taken together, these findings indicate it is possible that diabetes could promote tau phosphorylation via impaired insulin signaling in the brain." (PMID 24204343, 2013). "Importantly, the 15–20% improvement in insulin sensitivity observed with OLE supplementation is comparable to those seen with medications commonly used to treat diabetes." (PMID 23516412, 2013). "In some patients with diabetes mellitus, additional insulin therapy is needed." (PMID 23533796, 2013). "Knowledge on how to initiate and adjust insulin will be assessed by a Web-based multiple choice questionnaire, and attitudes regarding diabetes/insulin will be assessed by Diabetes Attitude Scale 3 at 3 time points—before, immediately after, and 6 months after the intervention." (PMID 23612462, 2013). "“Injection is painful” (3 years of insulin use/ 6 years of having diabetes)." (PMID 24164794, 2013). "Given the protective effect against mortality identified in patients with diabetes mellitus, insulin and glucose levels may also strongly affect the immune response." (PMID 23957291, 2013). "Various pharmacological approaches have been used to improve diabetes via different modes of action including stimulation of insulin release, inhibition of gluconeogenesis, increasing the number of glucose transporters and reduction of glucose absorption from the intestine." (PMID 23718315, 2013). "The increases of circulating adiponectin may improve insulin sensitivity in obese and diabetes patients." (PMID 24312343, 2013). "Similarly, PR late in pregnancy in rats produces progeny with normal circulating glucose and insulin levels at 1 week of age, but mild fasting hyperglycemia and hyperinsulinemia at 7–10 weeks and frank diabetes by 26 weeks." (PMID 23424667, 2013). "We assumed that insulin prescribed to patients with diabetes has an anti-inflammatory property and pulmonary administration of insulin might exert beneficial effects much more than intravenous administration." (PMID 23622115, 2013). "Some of the fears were connected with self-management behaviour; for instance, the family members were afraid that the person with diabetes might forget to take insulin." (PMID 24455251, 2013).
diabetes (continued). "Among T2DM subjects in the primary care setting, impairments in the physical aspect of HRQOL were evident in subjects who were obese or had diabetic complications whereas defects in the mental aspect of HRQOL were observed in patients with lower BMI or receiving insulin injections." (PMID 23964785, 2013). "The lack of glucagon increase after melatonin treatment in GK rats may be a consequence of impaired insulin secretion or disturbed α-cell sensitivity for glucose, as is characteristic in diabetes." (PMID 23535335, 2013). "Whether pharmacological modulation of mitochondrial Ca2+ uptake may, therefore, regulate insulin secretion in vivo, and might thus provide a new approach to improve glucose tolerance in some forms of diabetes mellitus, is an intriguing question for the future." (PMID 23149488, 2013). "Additionally, for diabetes patients who take insulin, C-peptide measurement allows indirect assessment of endogenous insulin production." (PMID 31942247, 2013). "DNA vaccination with insulin B-chain prevented diabetes onset in NOD and RIP-NP mice through a mechanism involving IL-4 production, and administration of a DNA vaccine encoding proinsulin was effective in both prevention and reversal of diabetes in NOD mice." (PMID 23405091, 2013). "Despite the fact that the group of diabetics showed high levels of insulin (18.93 ± 12.58), its effect may have been attenuated due to their inferior beta cell functionality and higher levels of IR when compared to subjects who only presented IFG." (PMID 23710466, 2013). "Diet-induced obesity resulted in cognitive impairment whose mechanisms are associated with vascular damage to the central nervous system and numerous metabolic abnormalities including dyslipidaemia and glucose intolerance, producing functional resistance to insulin and leptin (diabetes)." (PMID 23741384, 2013). "Type-2 diabetes mellitus (T2D) is a prevalent disorder of glucose homeostasis resulting from an imbalance between insulin secretion by pancreatic β cells and the sensitivity of peripheral tissues to insulin." (PMID 24098680, 2013). "Moreover, the simultaneous administration of metformin and honey up-regulated the diabetes-reduced insulin, LH, FSH and testosterone levels." (PMID 24639728, 2013). "Taken together, these findings indicate that insulin/IGF signaling might be impaired in the AD with diabetes brain, and this signaling might have an impact on aging and disease-related brain dysfunction." (PMID 24204343, 2013). "In this context it is of note that phaeochromocytoma-derived catecholamines not only worsen insulin sensitivity, but also insulin secretion via alpha-2- adrenoceptors in beta-cells, which may contribute to diabetes mellitus development." (PMID 24146977, 2013). "Both cytokines were increased by diabetes and reduced by insulin." (PMID 24367624, 2013). "Besides environmental factors, twin studies have demonstrated a strong heritability for diabetes and insulin related phenotypes." (PMID 23922971, 2013). "Although the long-term clinical implications of these results are unclear, fasting insulin and HOMA-IR have been shown to be sensitive predictive markers of diabetes, ischemic stroke, and coronary heart disease risk in the general population as well as in at-risk subjects." (PMID 23638799, 2013). "An alternative explanation is that insulin therapy was administered too late after diabetes induction and late glycemic control, initiated past the time-point when ureteric branching morphogenesis is at its peak, could not restore these deficits." (PMID 23516451, 2013). "Such a low eGFR also has implications for drug therapy for diabetes mellitus and, if undetected, could lead to complications such as lactic acidosis from metformin or hypoglycemia from sulfonylureas or insulin." (PMID 24228774, 2013).
diabetes (continued). "Furthermore, it is well established that obese youth are more insulin resistant than their leaner counterparts and more likely to develop diabetes than those with normal weight." (PMID 24454364, 2013). "The objective of the Advancing Insulin Management in General Practice (AIM@GP) trial was to determine the effectiveness of an insulin initiation strategy utilizing diabetes specialist and community retail pharmacy support to increase family physician insulin prescribing rates." (PMID 23433347, 2013). "Clearly, diabetes patients in profile 1 were significantly older, mostly female, more of them had had a stroke, and had a significantly higher prescription rate of both oral medication only and of the combination of oral and insulin medication." (PMID 23289605, 2013). "Next, we have investigated whether over-expression of the D4 peptide is also effective in improving insulin sensitivity in a mouse model of obesity and diabetes." (PMID 23585839, 2013). "On the other hand family members only talked about diabetes in connection with practical things, for example, whether injecting the insulin had been painful." (PMID 24455251, 2013). "Liver function may be improved in naringin-treated rats by decreased lipid peroxidation in diabetes, improvement of hepatic insulin signalling by naringenin and improved liver structure and function, as with the closely related flavonoids, rutin and quercetin." (PMID 23446977, 2013). "In this work, we have proposed a new mathematical model that is able to predict known physiological behaviors of normal and diseased states (including diabetes, hypertension) that are governed by the interaction of insulin and angiotensin II signalling pathways." (PMID 24400038, 2013). "Although sulphonylureas, biguanides, insulin sensitizers (thiazolidinediones), and other current drugs are valuable in the treatment of type 2 diabetes mellitus, their use is restricted by cost, limited pharmacokinetic properties, secondary failure rates, and accompanying side effects." (PMID 23762869, 2013). "Collectively, less than 5% of cases of early-adult onset monogenic diabetes may be caused by mutations in genes most commonly associated with permanent neonatal diabetes such as ABCC8, KCNJ11, IPF1, NEUROD1, CEL and INS." (PMID 24705260, 2013). "It has been hypothesized that insulin therapy in earlier stages of the natural history of diabetes could protect β-cells, preserving insulin secretory capacity and glycemic control over the time, as suggested by some small trials." (PMID 24348585, 2013). "Intranasal insulin has also emerged as a potential treatment for both obesity and diabetes." (PMID 23135822, 2013). "Ten of them (42%) were treated by oral medication and/or insulin injection therapy for diabetes." (PMID 24455286, 2013). "Not only is TNF-α correlated with diabetes progression, it has also been found to alter insulin-mediated glucose uptake in muscle cells in vitro, and has been implicated in the development of insulin resistance through studies knocking out its respective receptors." (PMID 24391596, 2013). "With FDA approvals for pediatric antipsychotic treatment down to age 5–6 years old for some SGA medications, there is a growing need to identify metabolic changes that can be detected in young children (e.g. insulin sensitivity changes that proceed over diabetes)." (PMID 23947389, 2013). "In addition, S2814D mice also developed glucose intolerance, impaired glucose-stimulated insulin secretion and lowered [Ca2+]cyt transients, which are hallmarks of pre-diabetes." (PMID 23516528, 2013). "Moreover, GSK3 inhibitors improve insulin sensitivity in rodent models of diabetes, alleviating hyperglycemia by decreasing hepatic gluconeogenesis and stimulating glycogen synthesis." (PMID 23819126, 2013).
diabetes (continued). "Prediabetic insulin resistance state however does not always lead to diabetes; enhanced secretion of insulin by β cells compensates for deficient insulin action in a considerable proportion of prediabetic individuals who do not develop T2D." (PMID 23308243, 2013). "People with diabetes suffer from high blood sugar levels, either because of low insulin production, (insulin being a hormone that regulates cell uptake of glucose) or because cells have become resistant to insulin's action." (PMID 23358247, 2013). "Interestingly, though insulin therapy is the known most effective method for diabetes, it cannot reverse adrenal gland enlargement." (PMID 24194784, 2013). "Mean peak insulin levels were significantly higher in cases of diabetes." (PMID 23557386, 2013). "In a study of 999 patients with known diabetes treated in 44 hospitals across the U.S., 16% percent of patients with type 1 diabetes and 35% of patients with type 2 diabetes (using insulin as outpatients) were treated with sliding-scale insulin alone." (PMID 24499564, 2013). "The analysis of the indicators related to the glucose metabolism showed a statistically significant difference between the plasma levels of the immunoreactive insulin in patients with IGT in comparison to those with diabetes – 31,06±28,05 vs.18,92±16,57 (p −0.006)." (PMID 23497617, 2013). "Adjustment for insulin attenuated the association between lactate and incident diabetes, while adjustment for glucose non-significantly inverted the association." (PMID 23383072, 2013). "Since insulin exerts potent growth-promoting effects during intrauterine development, a low birthweight in infants diagnosed with diabetes soon after birth might reflect reduced insulin secretion by the foetal pancreas due to β-cell dysfunction in utero." (PMID 24051999, 2013). "Loss of glucose-stimulated insulin secretion from pancreatic islet β-cells is one of the fundamental defects in the pathogenesis of type 2 diabetes (T2D) and portends overt diabetes in humans and in nonhuman primates (NHPs)." (PMID 23886319, 2013). "Survival of transplanted insulin-secreting cells produced from ductal cells was poor, and reduced yields following transplantation of ductal cells precluded physiological studies in mouse models of diabetes." (PMID 24252877, 2013). "If we keep on exploring the mechanism, perhaps we will find that there are only two prognoses of this form of diabetes: insulin-depending and non-insulin-depending diabetes which may be related to the initial onset." (PMID 23710177, 2013). "Although the mechanisms underlying the role of vitamin D in MetSyn remain incompletely explained, it was showed that 25(OH)D3 could be related to the occurrence of reduced insulin secretion and sensitivity, obesity, diabetes, and hypertension." (PMID 23855914, 2013). "It is therefore not surprising that we observed that the defaulters group had the lowest proportion of patients meeting targets for HbA1c, BP, or LDL-C during the time they were followed in the diabetes clinic and were more likely to be on insulin than discharged patients." (PMID 23938105, 2013). "As previously reported, Irs2-deficient mice displayed elevated levels of both insulin and leptin until the onset of frank diabetes when beta cells are no longer able to compensate for peripheral insulin resistance." (PMID 23741292, 2013). "We believe that starting an insulin pump together with an empowerment-based, person-centred education model leads to retention of improved glycaemic control, QoL, responsibility distribution and reduced diabetes-related conflicts in the family." (PMID 24354899, 2013). "Chinese individuals have a lower prevalence of diabetes and are less insulin resistant than Indians, so the results of the Chinese study may not be applicable to Asian Indian individuals." (PMID 23415113, 2013).